MIR9-1HG (MIR9-1 host gene)
Description:
May play a role in FOS signaling pathways involved in development and remodeling of neurons. Promotes transcription of the FOS promoter.
Synonyms: C1orf61; CROC4
Gene: Long non-coding RNA gene on chromosome 1 (156,404,243 to 156,456,987, reverse strand). Ensembl gene ENSG00000125462.
Subcellular location: Nucleus
Gene Ontology:
Biological process: miRNA-mediated post-transcriptional gene silencing
Cellular component: RISC complex
Diseases named in the same sentence as MIR9-1HG in open-access papers:
MIR9-1HG is named in the same sentence as 9 diseases in open-access papers, as found by Europe PMC text mining. Sharing a sentence is not in itself a finding about the gene and the disease.
MIR9-1HG shares sentences with these, for which no sentence is quoted: hepatocellular carcinoma (6 papers); cancer (4); tumor (4); colorectal cancer (1); Headache (1); liver disease (1); migraine (1); non-small cell lung carcinoma (1); psychiatric diseases (1).